TEAD3 (TEA domain transcription factor 3)
Description:
Transcription factor which plays a key role in the Hippo signaling pathway, a pathway involved in organ size control and tumor suppression by restricting proliferation and promoting apoptosis. The core of this pathway is composed of a kinase cascade wherein MST1/MST2, in complex with its regulatory protein SAV1, phosphorylates and activates LATS1/2 in complex with its regulatory protein MOB1, which in turn phosphorylates and inactivates YAP1 oncoprotein and WWTR1/TAZ. Acts by mediating gene expression of YAP1 and WWTR1/TAZ, thereby regulating cell proliferation, migration and epithelial mesenchymal transition (EMT) induction. Binds to multiple functional elements of the human chorionic somatomammotropin-B gene enhancer.
Synonyms: TEAD-3; TEAD5; TEF5; TEF-5; ETFR-1; DTEF-1
Tractability: Small molecule: a structure with a bound ligand is known. PROTAC: ubiquitination databases record sites on it; a small molecule that binds it is known.
Target class: Transcription factor
Chemical probes: GNE-7883 (high quality), VT104 (high quality)
Gene: Protein-coding gene on chromosome 6 (35,473,597 to 35,497,079, reverse strand). Ensembl gene ENSG00000007866.
Subcellular location: Nucleus
Pathways (Reactome):
Gene expression (Transcription): RUNX3 regulates YAP1-mediated transcription; YAP1- and WWTR1 (TAZ)-stimulated gene expression
Immune System: Regulation of PD-L1(CD274) transcription
Gene Ontology:
Molecular function: DNA-binding transcription factor activity; protein binding; RNA polymerase II-specific DNA-binding transcription factor binding; DNA-binding transcription factor activity, RNA polymerase II-specific; RNA polymerase II cis-regulatory region sequence-specific DNA binding; DNA binding
Biological process: asymmetric neuroblast division; hippo signaling; embryonic organ development; female pregnancy; regulation of transcription by RNA polymerase II; positive regulation of transcription by RNA polymerase II; regulation of DNA-templated transcription
Cellular component: chromatin; nucleoplasm; transcription regulator complex; nucleus
Genetic constraint (gnomAD): Loss-of-function variants: 15 observed, 53.06 expected, observed/expected ratio (o/e) 0.28, 90% interval 0.19 to 0.44. The upper end of that interval is the gene's LOEUF score, 0.44, which puts it in group 1 of 6, group 1 being the genes least tolerant of losing a copy. Missense variants: 407 observed, 561.7 expected, observed/expected ratio (o/e) 0.72, 90% interval 0.67 to 0.79. Synonymous variants: 210 observed, 225.12 expected, observed/expected ratio (o/e) 0.93, 90% interval 0.83 to 1.05.
Homologues: Orthologues: chimpanzee TEAD3 (99% identical), macaque TEAD3 (99% identical), rabbit TEAD3 (99% identical), pig TEAD3 (99% identical), mouse Tead3 (97% identical), rat Tead3 (97% identical), dog TEAD3 (97% identical), guinea pig TEAD3 (97% identical), zebrafish tead3a (78% identical), zebrafish tead3b (72% identical), Caenorhabditis elegans egl-44 (43% identical). Paralogues in human: TEAD1 (70% identical), TEAD4 (69% identical), TEAD2 (64% identical).
Diseases named in the same sentence as TEAD3 in open-access papers:
TEAD3 is named in the same sentence as 24 diseases in open-access papers, as found by Europe PMC text mining. Sharing a sentence is not in itself a finding about the gene and the disease. The quoted sentences say what the papers report.
melanoma (3 papers, 2024 to 2025). A malignant, usually aggressive tumor composed of atypical, neoplastic melanocytes. "Its role in promoting EMT and its association with poor survival outcomes highlight TEAD3 as a potential therapeutic target for melanoma treatment." (PMID 41034991, 2025). "Collectively, our results reveal that GAS6 + macrophages enhance glycolysis and oxidative phosphorylation to fuel GAS6 secretion, which interacts with high-risk TEAD3 + melanoma cells via the TYRO3 receptor." (PMID 41034991, 2025). "TEAD3 emerged as a central regulator of melanoma malignancy, with high expression associated with poor prognosis and aggressive tumor behavior." (PMID 41034991, 2025). "First, our experimental models primarily reflect features of acral melanoma and the identified high-risk TEAD3 + subgroup; thus, the generalizability to other melanoma subtypes (e.g., BRAF or NRAS mutant, or triple wild-type tumors) requires further validation." (PMID 41034991, 2025). "The enrichment of TEAD3 in high-risk melanoma cells and its association with M2 macrophage interactions suggest that TEAD3 not only drives intrinsic tumor aggressiveness but also modulates the tumor microenvironment (TME) to favor immune evasion and tumor growth." (PMID 41034991, 2025). "The upregulation of Mmut and the consequent accumulation of methylmalonic acid in high-risk TEAD3 + melanoma cells suggest that targeting these metabolic pathways could disrupt tumor progression mechanisms, particularly in aggressive subtypes such as acral melanoma." (PMID 41034991, 2025). "Collectively, these results demonstrate that TEAD3 is a critical regulator of melanoma progression across multiple cellular contexts and in vivo models, influencing tumor growth, invasion, and metastasis." (PMID 41034991, 2025). "Through integrated multi-omics analyses, we uncovered the critical role of TEAD3 in driving melanoma progression and its interaction with GAS6 + macrophages via the GAS6-TYRO3 axis." (PMID 41034991, 2025). "The results confirmed that TEAD3 was highly expressed in tumor tissues compared to normal tissues, further supporting its role as a potential driver of melanoma progression." (PMID 41034991, 2025). "Knockdown of Mmut in TEAD3 + melanoma cells significantly reduced methylmalonic acid levels in both PBS- and GAS6-treated groups." (PMID 41034991, 2025). "To validate these results at the protein level, we performed immunohistochemical staining for TEAD3 in human melanoma and adjacent normal tissues." (PMID 41034991, 2025). "This metabolic reprogramming enables GAS6 + macrophages to interact with TEAD3 + melanoma cells via the GAS6-TYRO3 ligand-receptor axis, promoting tumor proliferation, EMT, and metastasis." (PMID 41034991, 2025). "Risk forest plot analysis revealed that SFN, PLA2G4E, SERPINB5, WWC1, PAK6, and TEAD3 were the most influential genes in promoting melanoma malignancy." (PMID 41034991, 2025). "To validate the functional role of TEAD3 in melanoma progression, we performed a series of in vitro and in vivo experiments using multiple melanoma cell lines and syngeneic mouse models." (PMID 41034991, 2025). "In conclusion, our study elucidates the pivotal role of the GAS6–TYRO3 axis and TEAD3-driven metabolic reprogramming in promoting melanoma progression and immune evasion, with particular relevance in acral and other high-risk melanomas." (PMID 41034991, 2025). "Consistent with the results in SK-MEL-5 cells, TEAD3 knockdown in both A-375 and MM9H-1 cells led to significant suppression of proliferation, migration, and invasion, reinforcing the crucial role of TEAD3 across different genetic backgrounds of melanoma." (PMID 41034991, 2025). "Functional validation demonstrated that TEAD3 knockout suppressed melanoma proliferation, migration, and epithelial-mesenchymal transition (EMT) in vitro and in vivo." (PMID 41034991, 2025).
melanoma (continued). "To further generalize these findings, we extended the TEAD3 knockdown experiments to two additional melanoma cell lines, A-375 and MM9H-1." (PMID 41034991, 2025). "We define a TEAD3-driven melanoma subtype reliant on SCFA metabolic reprogramming and M2 macrophage crosstalk." (PMID 41034991, 2025). "To investigate how GAS6 secretion interacts with TEAD3 + melanoma cells, we isolated TEAD3 + tumor cells from a B16F10luc melanoma mouse model and treated them with either GAS6 or PBS (control) during vitro culture, followed by non-targeted metabolomics sequencing." (PMID 41034991, 2025). "Collectively, these findings reveal a critical metabolic-immune crosstalk whereby GAS6 reprograms propionate metabolism in TEAD3 + melanoma cells via Mmut-mediated MMA accumulation, which not only enhances cell aggressiveness but also fosters an immunosuppressive microenvironment." (PMID 41034991, 2025). "Functional assays demonstrated that Mmut knockdown reversed the GAS6-induced enhancement of migration in TEAD3 + melanoma cells, indicating that GAS6 promotes melanoma cell aggressiveness by dysregulating propionate metabolism through Mmut upregulation and methylmalonic acid accumulation." (PMID 41034991, 2025). "In addition, patients with melanoma who expressed lower levels of NF2, TEAD3, and TEAD4 were associated with longer OS than those who expressed lower levels of NF2, TEAD3, and TEAD4." (PMID 38515849, 2024). "Initially, we designed three independent siRNAs targeting TEAD3 and confirmed their knockdown efficiency in the SK-MEL-5 human melanoma cell line." (PMID 41034991, 2025). "To further evaluate the role of TEAD3 in a more clinically relevant and immunocompetent microenvironment, we utilized the YUMMER1.7 syngeneic mouse model, which closely mimics key characteristics of human immunotherapy-resistant melanoma." (PMID 41034991, 2025).
osteoporosis (3 papers, 2023 to 2025). A condition of reduced bone mass, with decreased cortical thickness and a decrease in the number and size of the trabeculae of cancellous bone (but normal chemical composition), resulting in increased fracture incidence. "Metastasis-associated lung adenocarcinoma transcript-1 (MALAT-1) protects against osteoporosis by inhibiting osteoclast differentiation via TEA domain family member 3 (Tead3)/NFATc1 signaling." (PMID 40873591, 2025). "Our findings suggest the therapeutic potential of developing agents that disrupt the TEAD3-NFATC1 interaction for treating osteoporosis and bone metastasis." (PMID 38493144, 2024).
ovarian carcinoma (2 papers, 2016 to 2017). A malignant neoplasm originating from the surface ovarian epithelium. "Association of TEAD3 and Hippo-YAP signaling pathway was found in renal clear carcinoma, ovarian cancer and hepatocellular carcinoma." (PMID 29050244, 2017). "In ovarian cancer initiated cells (OCICs), TEAD1, TEAD3 and TEAD4 were found to be expressed at significantly higher levels than in differentiated ovarian cancer cells." (PMID 26805820, 2016).
acral melanoma (1 paper, 2025). "Single-cell RNA sequencing of acral melanoma revealed TEAD3-enriched tumor cells interacting with M2 macrophages via the GAS6-TYRO3 axis." (PMID 41034991, 2025).
atherosclerosis (1 paper, 2018). A disease characterized by the build-up of fatty material and calcium deposition in the arterial wall resulting in partial or complete occlusion of the arterial lumen. "A recent study showed that TEAD3 is required for TGFβ signaling through association with Smad3 in human aortic SMCs in a risk locus for atherosclerosis." (PMID 29342503, 2018).
Burkitt lymphoma (1 paper, 2021). A rare form of malignant mature B-cell non-Hodgkin lymphoma. "In support of our results here, results presented in the Human Protein Atlas database indicate that RNA transcripts of YAP, TAZ, and the four TEAD family members (TEAD1, TEAD2, TEAD3, and TEAD4) are not detected in the EBV-infected Burkitt lymphoma cell line, Daudi." (PMID 34339458, 2021).
endometriosis (1 paper, 2025). The growth of functional endometrial tissue in anatomic sites outside the uterine body. "Furthermore, the identification of upregulated genes, such as SIRT1, SBDS, SRF, SPN, P2RX1, TEAD3, and SLITRK3, alongside downregulated genes, including KIF22, KIF25, GAS2L2, and HINT3, highlights a broad transcriptional reprogramming within endometriosis-affected tissues." (PMID 41516028, 2025).
glaucoma (1 paper, 2022). Increased pressure in the eyeball due to obstruction of the outflow of aqueous humor. "For example, CDCA8, HLA-B, RHOC, PPM1J, RPL10A, and TEAD3 are associated with glaucoma (P < 1 × 10−6)." (PMID 36450729, 2022).
liver cancer (1 paper, 2021). An epithelial or non-epithelial malignant neoplasm that arises from the liver. "Related to Hippo signaling, we also identified TEAD3, a lesser described member of the TEAD family involved in hippo signalling, as a tumor-promoting effector in liver cancer." (PMID 34313788, 2021).
lung adenocarcinoma (1 paper, 2024). A carcinoma that arises from the lung and is characterized by the presence of malignant glandular epithelial cells. "For instance, lung squamous cell carcinoma carries TEAD2, TEAD3, and TEAD4 amplification, and lung adenocarcinoma carries TEAD3 amplification." (PMID 38499647, 2024).
pancreatic ductal adenocarcinoma (1 paper, 2022). An infiltrating adenocarcinoma that arises from the epithelial cells of the pancreas. "More recently, TEAD3 was reported to involve in metastasis and associated with a poor prognosis in pancreatic ductal adenocarcinoma." (PMID 35739490, 2022).
preeclampsia (1 paper, 2021). Preeclampsia is a hypertensive disorder of pregnancy that is characterized by new-onset hypertension with proteinuria presenting after 20 weeks of gestation, and depending on mild or severe forms may initially present with severe headache, visual disturbances, and hyperreflexia. "We also observed high DMC density regions in genes for which placental DNAm and/or expression differences have been associated with preeclampsia, including INHBA, JUNB, TEAD3, NDRG1, and CGA." (PMID 33407091, 2021).
rhabdomyosarcoma (1 paper, 2023). A rare aggressive malignant mesenchymal neoplasm arising from skeletal muscle. "NFIA is required for the proliferation of cervical cells, ZBTB18 for rhabdomyosarcoma, and TEAD3 for the urinary tract cells." (PMID 37297004, 2023).
stomach adenocarcinoma (1 paper, 2022). "TEADs were altered about 14% (67 samples out of 478 samples) in patients with stomach adenocarcinoma, and the proportion of amplification in genetic alterations was 30% for TEAD3 and 36% for TEAD4." (PMID 35739490, 2022).
tumor (11 papers, 2013 to 2025). "Upon implantation into syngeneic mice, TEAD3 deficiency led to a pronounced reduction in tumor growth and attenuated EMT markers in IHC analysis, corroborating the results obtained with the B16F10luc model." (PMID 41034991, 2025). "Subcutaneous injection of TEAD3-KO and wild-type (WT) cells into mice revealed that TEAD3 deficiency significantly reduced tumor growth, as evidenced by lighter tumor weight and decreased bioluminescent signal intensity in live animal imaging." (PMID 41034991, 2025). "Yes-Associated Protein 1 (YAP1) is a transcriptional coactivator, which upon binding to many transcription factors, such as TEAD3 (Transcriptional Enhanced Associate Domain 3), regulates the Hippo-signalling pathway, contributing to tumor growth, and resistance." (PMID 37055532, 2023). "Our functional validation in vitro and in vivo confirmed that TEAD3 promotes tumor proliferation, invasion, and metastasis by inducing epithelial-mesenchymal transition (EMT)." (PMID 41034991, 2025). "Single-cell localization analysis of the risk genes demonstrated that only ADH7, SFN, WWC1, PAK6, and TEAD3 were detectable in the single-cell data, with TEAD3 being predominantly expressed in tumor cells." (PMID 41034991, 2025). "To further elucidate the reasons behind the high malignancy of tumor cells with elevated expression of TEAD3, we isolated tumor cells from single-cell data and categorized them into high-risk and low-risk cancer cells based on their TEAD3 expression levels." (PMID 41034991, 2025). "GAS6-TYRO3 signaling in TEAD3 + cells drove tumor aggressiveness by rewiring propionate metabolism, inducing methylmalonic acid accumulation via Mmut upregulation." (PMID 41034991, 2025). "Immunohistochemical (IHC) analysis of tumor tissues harvested on day 21 demonstrated that TEAD3-KO tumors exhibited reduced epithelial-mesenchymal transition (EMT), characterized by downregulation of N-cadherin and upregulation of E-cadherin." (PMID 41034991, 2025). "To further explore whether GAS6-induced MMA accumulation contributes to immunosuppression—a key rationale for targeting this pathway—we collected conditioned medium (CM) from four treatment groups of TEAD3 + tumor cells and co-cultured it with primary murine CD8+ T cells." (PMID 41034991, 2025). "Some TFs were specific for individual cell lines, others were shared between two cell lines, and a total of eight TFs were shared amongst all three tumor types, including TEAD1, TEAD2, TEAD3, TEAD4, GRHL2, RUNX2, AP1, and GATA6." (PMID 38912065, 2024). "This comparison showed a very high degree of overlap in the percentage of target loci where VGLL1 bound compared to those targets previously identified for TEAD1, TEAD2, TEAD3, and TEAD4 (p < 10e-370 for all 3 tumor cell lines)." (PMID 38912065, 2024). "Significant TFs identified within the enhancer regions include Fra1, TEAD3, EWS-ERG fusion, and FOXN3, which are responsible for cell growth, tumor suppression, and suppression of transcription of transforming growth factor and play a role in several cancers." (PMID 36936794, 2023). "TEAD2 and 4 were significantly upregulated in HNSCC samples as compared to their non-tumor counterparts, while TEAD1 and TEAD3 were markedly downregulated in cancerous samples relative to non-tumor samples." (PMID 30459528, 2018). "Furthermore, TF footprint analysis has revealed tumor cell-specific binding TFs, including hepatocyte nuclear factor (HNF) family members, TEA domain transcription factor 3 (TEAD3), and nuclear factor I B (NFIB)." (PMID 41035074, 2025). "We confirmed induction of TEAD1/2/4, but not TEAD3, by qPCR analysis in Apc mutant intestinal organoids in vitro, ApcMin mutant tumours in vivo and in Apcfl/fl knockout intestinal crypts in vivo." (PMID 33950519, 2021).
tumor (continued). "TEAD3 is a transcription factor and FRMD1 is an activating transcription factor binding which have important functions in the Hippo signaling pathway, a pathway involved in tumor suppression by limiting proliferation and boosting apoptosis." (PMID 34446027, 2021).
cancer (7 papers, 2021 to 2025). A tumor composed of atypical neoplastic, often pleomorphic cells that invade other tissues. "Significant TFs identified within the enhancer regions include SMAD2:SMAD3, EWS-ERG fusion, TWIST1, and TEAD3, which play important roles in regulation of transcription in transforming growth factors and embryonic development and are associated with cancers." (PMID 36936794, 2023). "TEAD3 is a component of the Hippo pathway implicated in a number of diseases including cancer." (PMID 37297004, 2023). "Our findings align with emerging efforts to target immunosuppressive metabolic pathways in cancer, and importantly, identify TEAD3 not only as a mediator of aggressiveness but also as a potential biomarker for stratifying patients who may benefit from combined metabolic-immune targeting." (PMID 41034991, 2025). "A pan-cancer differential TEADs expression identified a high expression of TEAD1, TEAD2, TEAD3, and TEAD4 in 3, 6, 5, and 12 types of cancer tissues, respectively." (PMID 38607003, 2024).
TEAD3 also shares sentences with these, for which no sentence is quoted: cyst (2 papers); Alzheimer disease (1); hepatocellular carcinoma (1); infection (1); lung squamous cell carcinoma (1); mammary tumor (1); prostate carcinoma (1); psychiatric diseases (1).